CUL1 (cullin 1)
Description:
Core component of multiple cullin-RING-based SCF (SKP1-CUL1-F-box protein) E3 ubiquitin-protein ligase complexes, which mediate the ubiquitination of proteins involved in cell cycle progression, signal transduction and transcription. SCF complexes and ARIH1 collaborate in tandem to mediate ubiquitination of target proteins. In the SCF complex, serves as a rigid scaffold that organizes the SKP1-F-box protein and RBX1 subunits. May contribute to catalysis through positioning of the substrate and the ubiquitin-conjugating enzyme. The E3 ubiquitin-protein ligase activity of the complex is dependent on the neddylation of the cullin subunit and exchange of the substrate recognition component is mediated by TIP120A/CAND1. The functional specificity of the SCF complex depends on the F-box protein as substrate recognition component. SCF(BTRC) and SCF(FBXW11) direct ubiquitination of CTNNB1 and participate in Wnt signaling. SCF(FBXW11) directs ubiquitination of phosphorylated NFKBIA. SCF(BTRC) directs ubiquitination of NFKBIB, NFKBIE, ATF4, SMAD3, SMAD4, CDC25A, FBXO5 and probably NFKB2. SCF(BTRC) and/or SCF(FBXW11) direct ubiquitination of CEP68. SCF(SKP2) directs ubiquitination of phosphorylated CDKN1B/p27kip and is involved in regulation of G1/S transition. SCF(SKP2) directs ubiquitination of ORC1, CDT1, RBL2, ELF4, CDKN1A, RAG2, FOXO1A, and probably MYC and TAL1. SCF(FBXW7) directs ubiquitination of CCNE1, NOTCH1 released notch intracellular domain (NICD), and probably PSEN1. SCF(FBXW2) directs ubiquitination of GCM1. SCF(FBXO32) directs ubiquitination of MYOD1. SCF(FBXO7) directs ubiquitination of BIRC2 and DLGAP5. SCF(FBXO33) directs ubiquitination of YBX1. SCF(BTRC) mediates the ubiquitination of NFKBIA at 'Lys-21' and 'Lys-22'; the degradation frees the associated NFKB1-RELA dimer to translocate into the nucleus and to activate transcription. SCF(CCNF) directs ubiquitination of CCP110. SCF(FBXL3) and SCF(FBXL21) direct ubiquitination of CRY1 and CRY2. SCF(FBXO9) directs ubiquitination of TTI1 and TELO2. SCF(FBXO10) directs ubiquitination of BCL2. SCF(BTRC) directs 'Lys-48'-linked ubiquitination of UBR2 in the T-cell receptor signaling pathway. The SCF(FBXO31) protein ligase complex specifically mediates the ubiquitination of proteins amidated at their C-terminus in response to oxidative stress.
Tractability: Small molecule: a structure with a bound ligand is known; it has a high-quality binding pocket. Antibody: its Gene Ontology location is reachable by antibodies, with high confidence. PROTAC: UniProt records ubiquitination sites on it; ubiquitination databases record sites on it; its protein half-life has been measured.
Gene: Protein-coding gene on chromosome 7 (148,697,914 to 148,801,110, forward strand). Ensembl gene ENSG00000055130.
Subcellular location (Human Protein Atlas): Nucleoplasm; Cytosol; Nucleoli
Pathways (Reactome):
Immune System: Activation of NF-kappaB in B cells; Antigen processing: Ubiquitination & Proteasome degradation; CLEC7A (Dectin-1) signaling; Dectin-1 mediated noncanonical NF-kB signaling; Downstream TCR signaling; FCERI mediated NF-kB activation; GSK3B-mediated proteasomal degradation of PD-L1(CD274); Interleukin-1 signaling; MAP3K8 (TPL2)-dependent MAPK1/3 activation; NIK-->noncanonical NF-kB signaling; Prolactin receptor signaling
Cell Cycle: Cyclin D associated events in G1; FBXL7 down-regulates AURKA during mitotic entry and in early mitosis; Regulation of PLK1 Activity at G2/M Transition; SCF(Skp2)-mediated degradation of p27/p21; SCF-beta-TrCP mediated degradation of Emi1; Ubiquitin-Mediated Degradation of Phosphorylated Cdc25A
Signal Transduction: Degradation of GLI1 by the proteasome; Degradation of GLI2 by the proteasome; Degradation of beta-catenin by the destruction complex; GLI3 is processed to GLI3R by the proteasome; NOTCH1 Intracellular Domain Regulates Transcription; Negative regulation of NOTCH4 signaling
Disease: Constitutive Signaling by NOTCH1 HD+PEST Domain Mutants; Constitutive Signaling by NOTCH1 PEST Domain Mutants; Loss of Function of FBXW7 in Cancer and NOTCH1 Signaling; Nuclear events stimulated by ALK signaling in cancer
Cellular responses to stimuli: GSK3B and BTRC:CUL1-mediated-degradation of NFE2L2; Regulation of BACH1 activity
Circadian clock: Degradation of CRY and PER proteins
DNA Replication: Orc1 removal from chromatin
Gene expression (Transcription): Regulation of RUNX2 expression and activity
Metabolism of proteins: Neddylation
Transport of small molecules: Iron uptake and transport
Gene Ontology:
Molecular function: protein binding; ubiquitin ligase complex scaffold activity; ubiquitin protein ligase binding
Biological process: cellular response to oxidative stress; positive regulation of canonical NF-kappaB signal transduction; proteasome-mediated ubiquitin-dependent protein catabolic process; protein K48-linked ubiquitination; protein ubiquitination; SCF-dependent proteasomal ubiquitin-dependent protein catabolic process; centrosome duplication; cilium assembly; G1/S transition of mitotic cell cycle; intracellular iron ion homeostasis; intrinsic apoptotic signaling pathway; limb development; neural crest cell differentiation; regulation of apoptotic process; regulation of BMP signaling pathway; regulation of cell cycle; regulation of cell cycle process; regulation of centrosome duplication; regulation of circadian rhythm; regulation of DNA damage checkpoint; regulation of DNA-templated transcription; regulation of inflammatory response; regulation of mitophagy; regulation of mitotic cell cycle; regulation of TOR signaling; and 2 more
Cellular component: cullin-RING ubiquitin ligase complex; Parkin-FBXW7-Cul1 ubiquitin ligase complex; plasma membrane; SCF ubiquitin ligase complex; cytoplasm; cytosol; nucleoplasm; nucleus
Genetic constraint (gnomAD): Loss-of-function variants: 17 observed, 86.67 expected, observed/expected ratio (o/e) 0.2, 90% interval 0.13 to 0.29. The upper end of that interval is the gene's LOEUF score, 0.29, which puts it in group 1 of 6, group 1 being the genes least tolerant of losing a copy. Missense variants: 302 observed, 806.56 expected, observed/expected ratio (o/e) 0.37, 90% interval 0.34 to 0.41. Synonymous variants: 276 observed, 306.16 expected, observed/expected ratio (o/e) 0.9, 90% interval 0.82 to 1.
Homologues: Orthologues: chimpanzee CUL1 (100% identical), macaque CUL1 (99% identical), mouse Cul1 (99% identical), dog CUL1 (99% identical), guinea pig CUL1 (99% identical), pig CUL1 (99% identical), rabbit CUL1 (99% identical), tropical clawed frog cul1 (99% identical), rat Cul1 (97% identical), zebrafish cul1a (97% identical), zebrafish cul1b (94% identical), Drosophila melanogaster Cul1 (63% identical), and 2 more. Paralogues in human: CUL2 (37% identical), CUL4A (31% identical), CUL4B (30% identical), CUL3 (30% identical), CUL5 (28% identical), ANAPC2 (15% identical), CACUL1 (7% identical).
Diseases named in the same sentence as CUL1 in open-access papers:
CUL1 is named in the same sentence as 70 diseases in open-access papers, as found by Europe PMC text mining. Sharing a sentence is not in itself a finding about the gene and the disease. The quoted sentences say what the papers report.
breast carcinoma (11 papers, 2012 to 2025). "CUL1 overexpression has also been associated with poor prognosis in gastric cancer, non-small-cell lung cancer, and breast cancer." (PMID 39588388, 2024). "Overexpression of CUL1 has been associated with poor prognosis in several cancers such as gastric cancer, breast cancer, and colon cancer, and has potential to be used as a prognosis marker." (PMID 37760968, 2023). "High expression of Cul1 is linked to the development of breast cancer by promoting proliferation, migration, and invasion of breast cancer cells and is associated with a poor prognosis." (PMID 36476410, 2022). "For those who carried the CLOCK rs11133373 CC genotype, increment of CUL1 rs758880 A genotype increased the breast cancer risk (OR = 1.84 [95% CI = 1.13–3.00]), but in GG genotype, it showed decreased associations significantly." (PMID 31358835, 2019). "Our previous study has showed that CUL1 is positively associated with poor overall and disease-specific survival of breast cancer patients." (PMID 30578411, 2018). "Our previous study has indicated that CUL1 is positively associated with poor 5-year overall and disease-specific survival of breast cancer patients." (PMID 30578411, 2018). "In contrast, in colorectal cancer, lower CUL1 expression correlates with better outcomes, while in breast cancer, reduced HIF3A levels indicate a more favorable prognosis." (PMID 40524221, 2025). "We, therefore, knocked down all five cullins (Cul-1, -2, -3, -4A, -4B, -5) individually, and found that only Cul-3 knockdown caused SLC7A11 accumulation in multiple breast cancer cell lines." (PMID 38959043, 2024). "CUL1 has also been investigated as a prognosis marker, particularly in breast cancer and colorectal cancer." (PMID 37760968, 2023). "For example, CUL1 is defined as a biomarker for breast cancer because it significantly promotes breast cancer cell migration, invasion, and test-tube formation, as well as angiogenesis and metastasis in vivo." (PMID 36984779, 2023). "Using TCGA breast cancer dataset, we found that CUL1 mRNA levels positively correlated with EZH2 mRNA expression." (PMID 30578411, 2018). "Our data showed that CUL1 significantly promoted breast cancer cell migration, invasion, tube formation in vitro, as well as angiogenesis and metastasis in vivo." (PMID 30578411, 2018). "In this study, we conducted a series of in vitro and in vivo experiments and the gene expression profiling to further perfect molecular mechanism of CUL1 in breast cancer metastasis." (PMID 30578411, 2018). "Our results exhibited that lung was the main target organ for breast cancer metastasis and the fluc activity in the CUL1 knockdown group is much lower than the control one." (PMID 30578411, 2018). "With regard to the potential of CUL1 in breast cancer migration, invasion, angiogenesis, and metastasis, we further investigated the molecular mechanism on the functional properties." (PMID 30578411, 2018). "Our data showed that CUL1 was highly expressed in breast cancer cells when compared with normal mammary epithelial cells." (PMID 30578411, 2018). "The roles of CXCL8 and IL11 in CUL1-regulated breast cancer metastasis were further validated by CXCL8 and IL11 rescue assays." (PMID 30578411, 2018). "CUL1 expression in the breast cancer cell lines was much higher than the normal mammary epithelial cell line." (PMID 30578411, 2018). "Since tumor metastasis involves sequential multi-steps, including angiogenesis, migration, invasion, and so on4, in our study, we designed a series of experiments to explore the roles of CUL1 in breast cancer metastasis." (PMID 30578411, 2018). "To confirm the role of CXCL8 and IL11 in CUL1 regulated breast cancer cell migration and angiogenesis, we performed CXCL8 and IL11 rescue assays." (PMID 30578411, 2018). "Together, these results showed that CUL1 played as an important regulator of breast cancer metastasis." (PMID 30578411, 2018).
breast carcinoma (continued). "To further elucidate the mechanism by which CUL1 regulates the breast cancer migration, invasion, metastasis, and angiogenesis, we conducted gene expression profiling of CUL1 knockdown and vector control MDA-MB-231 cells in triplicate." (PMID 30578411, 2018). "In all tested breast cancer lines, a portion of cullin-1 was neddylated, and cullin-1 neddylation was completely inhibited after 6 hrs of exposure to MLN4924 at 1 μM." (PMID 22457814, 2012). "Overexpression of CUL1 in normal mammary epithelial cells significantly increased the cell migration and invasion and showed the elongated fibroblast-like morphology through inducing EMT, while knockdown of CUL1 inhibited breast cancer cell migration, invasion, and tube formation in vitro." (PMID 30578411, 2018). "To investigate the oncogenic role of CUL1 in breast cancer, we firstly examined the CUL1 expression in the immortalized normal human mammary epithelial cell line MCF10A and a series of breast cancer cell lines including MDA-MB-231, MCF7, BT549 by western blotting." (PMID 30578411, 2018). "Combined with the previous report about CUL1, we proposed that CUL1 may serve as a promising therapeutic target for breast cancer metastasis." (PMID 30578411, 2018). "Then we investigated whether CUL1 exerted its effect on breast cancer cells metastasis through EZH2." (PMID 30578411, 2018). "Combined with our previous report about CUL1, we proposed that CUL1 may serve as a promising therapeutic target for breast cancer metastasis." (PMID 30578411, 2018). "In mechanism, the human gene expression profiling was used to determine global transcriptional changes in MDA-MB-231 cells, and we identified autocrine expression of the cytokines CXCL8 and IL11 as the target genes of CUL1 in breast cancer cell migration, invasion, metastasis, and angiogenesis." (PMID 30578411, 2018). "Our data indicated that CXCL8 and IL11 contributed to CUL1-regulated breast cancer metastasis." (PMID 30578411, 2018). "In this study, we elucidated this signaling pathway on CUL1-regulated breast cancer metastasis." (PMID 30578411, 2018). "It has been reported that CUL1, CUL2, CUL4A and CUL5 are efficiently deNEDDylated by MLN4924 in MCF breast cancer cells." (PMID 35880551, 2022). "Consistently, the significant positive correlations of CUL1 mRNA expressions with CXCL8 and IL11 mRNA expressions were observed in TCGA breast cancer dataset which includes 1153 breast cancer patients." (PMID 30578411, 2018). "CUL1 regulated EZH2 expression to promote the production of cytokines, and finally significantly aggravating the breast cancer cell metastasis and angiogenesis through the PI3K–AKT–mTOR signaling pathway." (PMID 30578411, 2018). "In addition, following 6 h treatment with MLN4924, CUL1, CUL2, CUL4A and CUL5 are efficiently deNEDDylated in MCF breast cancer cells." (PMID 35880551, 2022). "In addition, putative gene interactions between NPAS2, CUL1 and RORA, CLOCK and CUL1 is observed to have correlation in the development of breast cancer." (PMID 31358835, 2019). "Taken together, our data highlighted that CUL1 regulated EZH2 expression to promote the production of autocrine expression of the autocrine cytokines CXCL8 and IL11, and finally significantly aggravating the breast cancer cell metastasis through the PI3K–AKT–mTOR signaling pathway." (PMID 30578411, 2018).
melanoma (8 papers, 2012 to 2025). A malignant, usually aggressive tumor composed of atypical, neoplastic melanocytes. "The CUL1(e7)–BRAF(e9) fusion was previously observed in a few cases of melanoma and low-grade serous carcinoma (LGSC), and only once in CRC." (PMID 34657620, 2021). "CUL1 is a scaffold protein in the SCF E3 ubiquitin ligase complex that mediate the ubiquitination of proteins involved in cell proliferation in melanoma." (PMID 33428680, 2021). "Another example can be found in melanoma, where increased expression of CUL1 promotes cell proliferation through regulating p27 expression." (PMID 23935076, 2013). "ING4 and Cul1 had the most significantly statistical differences between dysplastic nevi and melanoma." (PMID 23028750, 2012). "Our previous studies found that 12 markers including pAkt, Bim, BRG1, BRMS1, CTHRC1, Cul1, ING4, MCL1, NQO1, SKP2, SNF5 and SOX4 were associated with melanoma progression." (PMID 23028750, 2012). "In addition, CUL1 overexpression improves the proliferative ability of melanoma cells by regulating the level of p27 and promotes the migration of human trophoblast cells." (PMID 39588388, 2024). "Cul1 had the most significant statistical difference between dysplastic nevi and melanoma." (PMID 23028750, 2012). "Cul1, a member of Cullin family, plays an important role in protein degradation and protein ubiquitination, is increased in early stages of human melanoma and promotes melanoma cell proliferation through regulating p27." (PMID 23028750, 2012). "The multiple biomarkers ING4, Cul1, BRG1 and Bim described here can aid in the discrimination of melanoma from dysplastic nevi and provide a new insight to help clinicians recognize melanoma." (PMID 23028750, 2012). "The differential expressions of Bim, BRG1, Cul1 and ING4 between melanoma and dysplastic nevi were confirmed by the multiple logistic regressions (p < 0.05)." (PMID 23028750, 2012). "Four (Bim, BRG1, Cul1 and ING4) of 12 markers were significantly differentially expressed in melanoma compared with dysplastic nevi by both univariate and multiple logistic regression analysis (p < 0.01)." (PMID 23028750, 2012). "We found that Bim, BRG1, Cul1 and ING4 were differently expressed between melanoma and dysplastic nevi using the univariate logistic regression (p < 0.01)." (PMID 23028750, 2012). "Immunohistochemical expressions of 12 promising biomarkers (pAkt, Bim, BRG1, BRMS1, CTHRC1, Cul1, ING4, MCL1, NQO1, SKP2, SNF5 and SOX4) were studied in 122 melanomas and 33 dysplastic nevi on tissue microarrays." (PMID 23028750, 2012). "The results demonstrated that the expression of Bim, BRG1, Cul1 and ING4 differed significantly between melanoma and dysplastic nevi, using the optimal scale partitioning of negative, weak to moderate and strong staining of these markers." (PMID 23028750, 2012). "In summary, we describe a multi-marker immunohistochemical panel of Bim, BRG1, Cul1 and ING4 which may aid in differential diagnosis for melanoma from dysplastic nevi." (PMID 23028750, 2012).
viral infection (8 papers, 2016 to 2025). "Knockdown of CUL2 and to a lesser extent CUL1 using siRNA stabilized SAMHD1 in normal fibroblasts and inhibited SAMHD1 loss during virus infection." (PMID 32850489, 2020). "We first validated the initially observed interactions between NSP1 and Rbx1, Cul1, Cul3 and β-TrCP by co-immunoprecipitation (IP) of transiently overexpressed NSP1s, Rbx1 and Cul3 and in the context of virus infection." (PMID 27706223, 2016). "Both viruses exhibit marginal effects on Cullin 1 neddylation but might enhance global neddylation since more neddylated proteins were detected by histidine pulldown after viral infection." (PMID 34506605, 2021). "A previous study has revealed that a Cullin 1-based ubiquitin E3 ligase mediates ubiquitin-dependent protein turnover of IRF7 before and after viral infection in most cell types." (PMID 34506605, 2021). "The C2 protein of Tomato yellow leaf curl Sardinia virus (TYLCSV) interacts with CNS5 (a component of the COP9 signalosome) to disrupt the interaction between CUL1 and SCF ubiquitination activity, thereby suppressing JA biosynthesis for promoting viral infection." (PMID 41157791, 2025). "Thus, we assume that P6–LsCSN5 interaction inhibits the CUL1-based E3 ligase-mediated degradation of other targets than the TIM protein, which would contribute to other important functions of BYSMV P6 in virus infections." (PMID 37717061, 2023). "Unlike closely related protein family members Cul1, Cul4 and Cul5, which are hijacked by HIV-1 to support viral infection, our data demonstrate that Cul3 acts as a negative regulator of HIV-1 infection and further elucidate the mode of action by which Cul3 exerts this restrictive effect on HIV-1." (PMID 32882949, 2020).